USP5 (ubiquitin specific peptidase 5)
Diseases named in the same sentence as USP5 in open-access papers (continued):
Sharing a sentence is not in itself a finding about the gene and the disease.
ovarian serous carcinoma (1 paper, 2019). "Kaplan-Meier survival analysis revealed that high expression of USP5 was closely associated with poor overall survival of patients with ovarian serous carcinomas." (PMID 31727867, 2019). "In the present study, we reported that the highly prevalent rate of USP5 gene amplification was closely associated with poor prognosis of patients with ovarian serous carcinomas." (PMID 31727867, 2019). "Survival analysis on cohort 1 also confirmed the prognostic value of USP5 amplification in ovarian serous carcinomas (P<0.05)." (PMID 31727867, 2019). "USP5 expression showed a positive correlation with tumor size, tumor grade and poor prognosis of ovarian serous carcinomas patients." (PMID 31727867, 2019). "USP5 amplification and overexpression was positively correlated with poor prognosis of patients of ovarian serous carcinomas." (PMID 31727867, 2019). "HDAC2 protein was positively correlated USP5 protein, and negatively correlated with p27 protein in ovarian serous carcinomas tissues." (PMID 31727867, 2019). "In ovarian serous carcinomas tissues, a positive correlation was observed between the protein expression of USP5 and HDAC2." (PMID 31727867, 2019). "In the present study, CNV analysis on USP family members revealed that USP5 amplification was common in ovarian serous carcinomas and that patients with USP5 amplification had a poor prognosis compared to patients without USP5 amplification." (PMID 31727867, 2019). "Pearson correlation analysis revealed that HDAC2 protein expression was positively correlated with USP5 protein expression, and negatively correlated with p27 protein expression in ovarian serous carcinomas tissues (P<0.0001)." (PMID 31727867, 2019). "Multivariate Cox regression analysis revealed that USP5 expression was an independent prognostic marker for ovarian serous carcinomas (P<0.05)." (PMID 31727867, 2019). "The upregulation of USP5 protein was also observed in ovarian serous carcinomas tissues." (PMID 31727867, 2019). "The effects of USP5 CNV on mRNA expression were then evaluated by GISTIC analysis, and the results showed that USP5 amplification was associated with higher mRNA expression of USP5 in ovarian serous carcinomas patients." (PMID 31727867, 2019). "In summary, this is the first study to investigate a molecular link connecting USP5, HDAC2, and p27 in ovarian serous carcinomas." (PMID 31727867, 2019). "CNV analysis performed on TCGA ovarian serous carcinomas dataset revealed that 8 members of USP displayed copy-number amplification in patients with ovarian serous carcinomas (n=579), and USP5 had the highest amplification rate." (PMID 31727867, 2019). "Importantly, targeting USP5 might bring novel therapeutic options for ovarian serous carcinomas." (PMID 31727867, 2019). "By analyzing TCGA ovarian serous carcinomas expression dataset, we found that HDAC Class I pathway was significantly correlated with USP5 expression." (PMID 31727867, 2019). "By Gene set enrichment analysis (GSEA) of TCGA ovarian serous carcinomas dataset, HDAC Class I pathway was found to be significantly correlated with USP5 expression." (PMID 31727867, 2019). "We then detected USP5 protein expression by immunohistochemical staining in 84 ovarian serous carcinomas tissues and 12 noncancerous ovary tissues (cohort 2)." (PMID 31727867, 2019).
renal cell carcinoma (1 paper, 2023). "The result of CPTAC analysis indicated that the protein expression of USP5 was up-regulated and correlated with pathological stages in clear cell RCC (renal cell carcinoma) and OV." (PMID 37268697, 2023).
Sepsis (1 paper, 2023). Sepsis is defined as life-threatening organ dysfunction caused by a dysregulated host response to infection. "Next, we identified TXNIP deubiquitination, mediated by the deubiquitinating enzyme USP5, as a novel mediator of sepsis-induced liver injury." (PMID 37534934, 2023). "Although our study suggests that the knockdown USP5 could be an effective method for alleviating sepsis-induced liver injury by reducing TXNIP stability, several limitations should be considered." (PMID 37534934, 2023). "Therefore, targeting USP5/TXNIP may be an important therapeutic strategy for sepsis-mediated liver injury." (PMID 37534934, 2023). "The results showed that the mRNA levels of IL-18, IL-1β, and procaspase-1 decreased after knockdown of USP5 in LPS-induced sepsis cell model, and overexpressed TXNIP in USP5 knockdown cells could upregulate the inflammatory factors." (PMID 37534934, 2023).
tumor (56 papers, 2013 to 2026). "Among them, the Stress subpopulation emerged as a distinct subset characterized by significant USP5 upregulation, which was strongly associated with tumor progression and poor prognosis." (PMID 40066708, 2025). "This study revealed that the Stress subpopulation, characterized by USP5 upregulation, was associated with enhanced tumor cell proliferation, migration, and invasion." (PMID 40066708, 2025). "We found that THP1-derived macrophages (THP1-MΦ) cocultured with IFN-β–treated USP5-deficient tumor cells exhibited upregulated ISG15, IFI44, CXCL9, and CXCL10 mRNA expression." (PMID 41321309, 2025). "These organoids, which retain the genetic, molecular, and phenotypic features of the original tumor, provide a robust ex vivo platform to assess the functional impact of USP5 depletion on ferroptosis susceptibility and tumor growth dynamics." (PMID 41213937, 2025). "These associations suggest that USP5 plays a key role in promoting tumor growth and survival while simultaneously inhibiting tumor‐suppressive mechanisms." (PMID 40066708, 2025). "Elevated expression of USP5 is associated with larger tumor sizes and poorer differentiation in non‐small cell lung cancer (NSCLC), underscoring its role in tumor progression." (PMID 39678489, 2024). "Next, we utilized several subcutaneous mouse tumor models to evaluate how Usp5 deficiency in T cells affects tumor growth in mice." (PMID 37208329, 2023). "And the detection of ferroptosis‐associated markers in xenograft tumor samples with USP5 overexpression also showed that ACSL4 decreased, and SLC7A11 increased." (PMID 37492786, 2023). "Together, these results show that Usp5 deficiency in T cells enhances anti-tumor immunity largely through reducing the PD-1 expression in CD8+ T cells." (PMID 37208329, 2023). "As expected, overexpression of mPD-L1 significantly undermined tumor suppressive effect caused by USP5 knockdown." (PMID 34741014, 2021). "Overall, USP5 upregulation is associated with tumor metastasis and poor prognosis in patients with NSCLC." (PMID 32477134, 2020). "Usp5 deficiency resulted in reduced PD-1 protein level in tumor-infiltrating CD8+ T cells." (PMID 37208329, 2023). "To further test whether USP5 knockdown caused LCC tumor growth inhibition was resulted from PD-L1downregulation, we next performed T cell-mediated cancer cell killing assay." (PMID 34741014, 2021). "In addition, we are the first to find that high USP5 expression is significantly associated with tumor metastasis in NSCLC, endowing USP5 with a new function in tumor progression." (PMID 32477134, 2020). "The expression of USP5 was associated with tumour metastasis." (PMID 31845546, 2020). "Furthermore, this correlation could be observed in tumor xenografts, with immunostaining of paraffin tissue sections showing that USP5 silencing caused a reduction in β-catenin expression." (PMID 37726816, 2023). "Taken together, we speculated that increased USP5 level is associated with tumor metastasis." (PMID 33123271, 2020). "Functional assays demonstrated that USP5 knockdown suppressed cell proliferation in vitro and inhibited tumor growth in vivo, accompanied by a reduction in purine metabolism." (PMID 41922317, 2026). "Our current study further elucidated the immunosuppressive role of tumor-intrinsic USP5 by revealing its inhibition of IFN-I–mediated macrophage reprogramming and antitumor immune responses." (PMID 41321309, 2025). "Patient-derived organoids and xenograft models confirmed that USP5 knockout significantly inhibits tumor growth and enhances ferroptosis sensitivity, with Fer-1 partially reversing this effect." (PMID 41213937, 2025).
tumor (continued). "In the present study on ESCC, we have demonstrated for the first time that USP5 is an effector enzyme in Notch signaling activation-induced tumor angiogenesis." (PMID 40691441, 2025). "How tumor-intrinsic IFN-I signaling in USP5-depleted cells activates macrophages warrants further investigation." (PMID 41321309, 2025). "Depletion of USP5 permits the transfer of p-STAT1/2 from tumor cells to macrophages in an LC3- and autophagy-dependent manner, conferring an immunostimulatory phenotype of macrophages." (PMID 41321309, 2025). "In patient-derived organoid and xenograft models, USP5 knockout significantly increased the sensitivity of cancer cells to ferroptosis and inhibited tumor growth." (PMID 41213937, 2025). "In vivo experiments further demonstrated that overexpression of RACK1 and USP5 alleviated the inhibitory effects of LRP11 knockdown on tumor proliferation, confirming their crucial role in mediating LRP11-driven HCC growth." (PMID 39891099, 2025). "We showed that chemotherapy combined with the USP5 inhibitor can additionally repress tumor growth and angiogenesis in mice." (PMID 40691441, 2025). "USP5 depletion boosts radiation-induced macrophage-mediated antitumor immunity through tumor cell–intrinsic IFN-I signaling." (PMID 41321309, 2025). "Our study provided compelling evidences that the natural compound α-hederin exerts anti-tumor effects by directly targeting USP5, disrupting its interaction with STAT3, and inhibiting STAT3 deubiquitination-a previously unreported mechanism." (PMID 41281755, 2025). "To evaluate the physiological relevance of USP5-mediated ferroptosis regulation in vivo, we employed a xenograft tumor model." (PMID 41213937, 2025). "Conditional knockout of Usp5 in T cells enhances effector cytokine production and slows tumor growth in mice." (PMID 40040703, 2025). "Immunohistochemistry (IHC) analysis demonstrated markedly increased USP5 expression in tumor tissues compared to adjacent normal tissues." (PMID 41213937, 2025). "USP5 interacts with PD-1, leading to its deubiquitination and stabilization, thereby modulating tumor immunotherapy." (PMID 39891099, 2025). "Taken together, our results indicate that depletion of tumor-intrinsic USP5 triggers the transfer of p-STATs from tumor cells to macrophages, inducing CXCL9+ macrophage and CD8+ T cell antitumor immunity." (PMID 41321309, 2025). "Our results also demonstrate that inhibiting the Notch/USP5 signaling significantly reduces the microvascular density and tumor volume in mice and significantly increases the tumor suppressive effect of chemotherapy for ESCC." (PMID 40691441, 2025). "Our data suggest that USP5 depletion in tumor cells drives LC3-related secretory autophagy of p-STAT1/2, resulting in intercellular transference of IFN-I signaling and macrophage activation." (PMID 41321309, 2025). "As expected, flow cytometric analysis showed the occurrence of an EGFP+ subpopulation in THP1-MΦ treated with LEVs from the USP5-depleted tumor cells." (PMID 41321309, 2025). "USP5 plays a crucial role in the tumor development and progression, and is a potential target for cancer therapy 28, 35-37." (PMID 39897046, 2025). "These alterations suggest that USP5 plays a multifaceted role in promoting tumor progression and metastasis." (PMID 40066708, 2025). "It further revealed that USP5 promoted tumor cells growth and enhanced their resistance to the chemotherapeutic drug doxorubicin by deubiquitinating Tu translation elongation factor (TUFM)." (PMID 41281755, 2025). "Subsequent analysis of MDA also indicated that USP5 knockout led to a significant increase in MDA levels in tumor tissues, whereas Fer-1 treatment markedly reduced this increase." (PMID 41213937, 2025). "Analysis of 12 paired CRC tumor and adjacent normal tissues further confirmed significantly higher USP5 expression in most tumor samples." (PMID 41213937, 2025).
tumor (continued). "Altered USP5 expression levels not only influenced tumor cell proliferation and migration but also had significant effects on cell cycle regulation and epithelial–mesenchymal transition (EMT)." (PMID 40066708, 2025). "In the TCGA-KIRC cohort, USP5 expression was significantly increased in ccRCC tumour tissues, and its mRNA levels were strongly correlated with lymph node and distant metastasis." (PMID 40435846, 2025). "Flow cytometric analyses demonstrated that USP5-IN-1 treatment increased tumor-infiltrating macrophages and their iNOS+ subpopulation in CT26 tumors after irradiation." (PMID 41321309, 2025). "In this study, we found that IFN-I is related to CXCL9+ macrophages and CD8+ T cell immunity in NPC, and then identified that tumor-intrinsic USP5 is a key suppressor of this IFN-I–activated antitumor immunity." (PMID 41321309, 2025). "To investigate the clinical significance of USP5/EphA2 axis, we used IHC to detect expression levels of USP5 and EphA2 in 119 tumor tissues from patients with NPC, who received radical radiotherapy and concurrent chemotherapy according to a uniform guideline." (PMID 39897046, 2025). "The results in the current study not only deepen our understanding of the molecular mechanisms driving angiogenesis in ESCC but also suggest USP5 as a promising therapeutic target for disrupting tumor angiogenesis." (PMID 40691441, 2025). "We performed gene set enrichment analysis (GSEA) and identified enrichment of extracellular transport and exocytosis in NPC tumor cells with low USP5 expression." (PMID 41321309, 2025). "This dual effect indicates that USP5 knockdown exerts anti‐tumor effects by modulating these critical molecular pathways." (PMID 40066708, 2025). "Inhibition of USP5 facilitates LC3-dependent intercellular transfer of P-STAT1/2 between tumor cells and macrophages, which thus elicits CXCL9+ macrophages and enhances radiation-induced antitumor immunity." (PMID 41321309, 2025). "The study also highlights the depletion of USP5 as a stimulus for the transfer of IFN-I signaling from tumor cells to macrophages, thus reprogramming macrophages to IFN-I–responsive cells with potent antitumor activity, which enhances radiotherapy efficacy." (PMID 41321309, 2025). "This interaction underscores the significance of the USP5-Twist1 axis in cancer biology, particularly in the context of tumor metastasis and progression." (PMID 38474186, 2024). "The tumour volume in nude mice injected with USP5-knockout cells was significantly smaller than that in nude mice injected with the control T24 cells, and the tumours in the USP5-knockout group grew markedly slower than those in the WT T24 cell-injected group." (PMID 38229092, 2024). "USP5 overexpression notably promoted tumor growth in nude mice, while transduction of shUSP5 decreased the growth rate of xenograft tumors." (PMID 38973363, 2024). "EOAI, an inhibitor of USP5 deubiquitinating enzymes, showed a dose-dependent tumor growth inhibition in our results." (PMID 36611139, 2023). "Our results showed that USP5 largely localizes in the cytoplasm of tumor-infiltrating CD3+ T cells albeit some signal for USP5 can be observed in the nuclear." (PMID 37208329, 2023). "Mice with conditional knockout (cKO) Usp5 in T cells have better tumor control than wild-type (WT) mice." (PMID 37208329, 2023). "Conditional knockout of Usp5 in T cells increases the production of effector cytokines and retards tumor growth in mice." (PMID 37208329, 2023). "To investigate the role of USP5 in tumor metastasis, we established a lung metastasis mouse model by subcutaneously injecting CL1-5 cells stably expressing firefly luciferase into the left posterior flank of NOD-SCID mice." (PMID 37726816, 2023).